AQP5 (aquaporin 5)
Diseases named in the same sentence as AQP5 in open-access papers (continued):
Sharing a sentence is not in itself a finding about the gene and the disease.
Sepsis (continued). "Substitution of C for A at position −1364 was associated with decreased AQP5 protein expression and was a strong and independent prognostic factor for decreased 30-day mortality in patients with severe sepsis." (PMID 27871297, 2016). "A role for an additional AQP channel, AQP5, in neutrophil locomotion was suggested after observing the impaired neutrophil tissue infiltration and increased survival in severe sepsis in subjects with srs3759129 polymorphism, which was accompanied by reduced neutrophil AQP5." (PMID 40558507, 2025). "Subsequent multiple proportional hazard analysis substantiated the association between AC/CC genotypes and a diminished risk of mortality within 90 days, thereby corroborating the AQP5 -1364A/C polymorphism as an independent prognostic factor in sepsis, with implications for precision medicine." (PMID 39544938, 2024). "Notably, the -1364 A/C (rs3759129) polymorphism in the promoter region of the AQP5 gene has been extensively studied by our group in the context of sepsis." (PMID 39544938, 2024). "Furthermore, the C-allele of the AQP5 A(-1364)C-promoter polymorphism is not only associated with a lower AQP5 expression but also with reduced neutrophil migration and reduced 30-day mortality in severe sepsis." (PMID 38203778, 2024). "The C-allele of the aquaporin (AQP5)-1364A/C polymorphism was shown to be associated with decreased AQP5 expression, which was shown to be relevant in this context leading towards improved outcomes in sepsis." (PMID 36233114, 2022). "As the A-allele is associated with decreased promoter methylation, increased AQP5 expression and worse outcome in sepsis, the treatment with epigenetic drugs could maybe provide benefit." (PMID 36233114, 2022). "For example, high AQP5 mRNA expression in the blood of patients with sepsis was related to a higher mortality rate that was associated with greater AQP promotor methylation at a putative nuclear factor kappa-light-chain-enhancer of activated B cells (NF-κB) binding site." (PMID 33567720, 2021). "Since C-allele carriers are associated with a lower AQP5 expression in sepsis compared to the AA genotypes, the AC/CC genotypes may confer an altered immune response." (PMID 32272738, 2020). "Since the functionally important AQP5 -1364A/C single nucleotide promoter polymorphism alters key mechanisms of inflammation and survival in sepsis, it may affect the risk of an acute kidney injury." (PMID 32272738, 2020). "Our results could be considered contradictory as the AA genotype of the AQP5 −1364A/C SNP was found to be associated with worse outcome in our previous studies on sepsis and ARDS." (PMID 31867018, 2019). "Notably, diseases with potentially exaggerated inflammatory responses, such as sepsis or ARDS, are associated with an attenuated AQP5 expression, as demonstrated in different sepsis settings in human and rodent models." (PMID 31811204, 2019). "AQP5 seems to be of special interest, because in the past our group demonstrated that the C-allele of the functional AQP5 A(-1364)C promoter polymorphism (rs3759129) is associated with increased survival in severe sepsis but decreased AQP5 expression." (PMID 29449936, 2018). "In the search for these mechanisms, our previous research suggested an impact of a decreased AQP5 expression in C-allele carriers on sepsis survival via its influence on the renin–angiotensin–aldosterone system, which however could not be confirmed." (PMID 27871297, 2016). "Furthermore, we showed that the C-allele, associated with decreased AQP5 expression and increased survival from severe sepsis, is associated with a decreased neutrophil cell migration in vitro." (PMID 27871297, 2016). "Our previous association study suggested that AQP5 seems to be a key protein in severe sepsis." (PMID 27871297, 2016).
Sepsis (continued). "Our investigation of Aqp5-KO mice in comparison with WT mice now confirms our hypothesis that the AQP5 expression itself has a particularly strong influence on the mortality of sepsis and that this influence is associated with decreased neutrophil migration." (PMID 27871297, 2016). "Thus, the link between the AQP5-1364A/C polymorphism and sepsis survival could be due to AQP5 expression and its impact on neutrophil cell migration." (PMID 27871297, 2016). "The findings emphasize the potential prognostic significance of AQP5 expression variations in severe sepsis, underscoring the role of AQP5 channels in influencing patient outcomes." (PMID 39544938, 2024). "As we surely cannot elucidate all effects of sepsis, we focus here on the impact on AQP5 expression, which was shown to be important in sepsis survival." (PMID 38203778, 2024). "This suggests that AQP5 plays a role in modulating immune responses and survival outcomes in sepsis." (PMID 39544938, 2024). "anshinol treatment in a rat sepsis model has been demonstrated to significantly increase AQP5 mRNA expression and reduce inflammatory cytokines IL-6 and TNF-α." (PMID 39544938, 2024). "Epigenetic regulation via DNA methylation also contributes to a differential AQP5 expression in sepsis." (PMID 39768394, 2024). "This indicates that epigenetic regulation of AQP5 via NF-κB binding at nt-937 is of pivotal importance in influencing the outcome of sepsis, thereby underscoring the potential prognostic significance of AQP5 promoter methylation in septic patients." (PMID 39544938, 2024). "AQP1 and AQP5 expression has been found to be downregulated by numerous investigators in experimental models of sepsis-induced ARDS." (PMID 38203657, 2023). "Interestingly, modulation of AQP5 expression is associated with altered neutrophil function, and there is increasing evidence that the AQP5 expression level in immune cells impacts survival rate in sepsis patients, proposing AQP5 as an interesting immune-modulatory therapeutic target." (PMID 33567720, 2021). "Certainly, AQP5 significantly impacts upon key mechanisms of inflammation that prevail in sepsis, including immune cell migration and proliferation." (PMID 32272738, 2020). "The crucial effect of this AQP5 SNP in mediating key mechanisms of inflammation and altering related host–pathogen communication was demonstrated in patients with sepsis and acute respiratory distress syndrome." (PMID 31867018, 2019). "Recently it was demonstrated that Aqp5 expression is decreased after sepsis induction with cecal ligation puncture (CLP) in the lung of rats." (PMID 29449936, 2018). "As a therapeutic option it was demonstrated that hydrogen rich saline and parenteral vitamin C can be protective in sepsis related lung injury and that it can attenuate the LPS induced reduction of Aqp1 and Aqp5 expression." (PMID 29449936, 2018). "Previous studies have suggested that AQP5 seems to be a key protein of inflammation in severe sepsis and ARDS." (PMID 30517197, 2018). "If AQP5 influences maturation the impact on cell migration would only be indirectly but it would still have the same impact on course of sepsis." (PMID 27871297, 2016). "Thus, they concluded that decreased AQP5 gene expression seemed to enhance survival by reducing the inflammatory burden during sepsis." (PMID 39768394, 2024). "As methazolamide reduces AQP5 mRNA expression and immune cell migration, this could represent a new therapeutic strategy for sepsis treatment." (PMID 38203778, 2024). "This study elucidated potential novel therapeutic options for sepsis therapy, as it was demonstrated that the deteriorating AQP5 mRNA expression in immune cells can be downregulated by the sulfonamide methazolamide and it is also capable of reducing immune cell migration." (PMID 38203778, 2024). "Hence, our study indicates that methazolamide is capable of reducing AQP5 expression and has the potential to be used in sepsis prophylaxis." (PMID 38203778, 2024).
Sepsis (continued). "This suggests that AQP5 promoter methylation may represent a potential target for interventions in sepsis." (PMID 39544938, 2024). "Novel therapeutic options are urgently needed and aquaporin inhibitors could suffice as aquaporin 5 (Aqp5) knockdown provided enhanced sepsis survival in a murine sepsis model." (PMID 38203778, 2024). "Another study has elucidated that downregulation of AQP5 could inhibit immune cell migration and inflammatory reaction during sepsis." (PMID 35538066, 2022). "Differential expression of AQP5 due to the methylation density might impact on immune cell migration, a possible key mechanism in sepsis." (PMID 36233114, 2022). "Accordingly, we assume that increased mortality in AA genotypes in sepsis is more likely to be mediated by aggravated inflammation or a more deleterious host response than due to the role of AQP5 in renal water transport, fluid balance, or impact on the RAAS system." (PMID 32272738, 2020). "We detected a functionally important AQP5 promoter CpG site (nt-937) linked to the binding of the inflammatorily acting nuclear transcription factor NF-κB, with increased methylation in sepsis non-survivors." (PMID 31811204, 2019). "However, regulation of AQP5 expression varies in sepsis patients, and greater (or “less suppressed”) AQP5 expression was accompanied by an increased 30-day mortality." (PMID 31811204, 2019). "We detected a functionally important AQP5 promoter cytosine site (nt-937) linked to the binding of the inflammatorily acting nuclear transcription factor NF-κB, with increased methylation in sepsis non-survivors." (PMID 31811204, 2019). "In this context, our findings may also provide a rationale that dissimilar AQP5 expression in sepsis may be facilitated by an altered NF-κB binding ability attributable to CpG methylation rather than NF-κB protein expression." (PMID 31811204, 2019). "Thus, AQP5 is involved in a lot of pathophysiological properties that prevail in sepsis and its altered expression seems to represent a crucial regulatory mechanism." (PMID 31811204, 2019). "In summary, the AQP5 genotype and AQP5 protein expression seem to alter neutrophil cell migration and may influence survival in sepsis by altering neutrophil cell migration." (PMID 27871297, 2016). "However, only methazolamide pre-treatment showed potential to reduce LPS-induced AQP5 expression, suggesting it may be useful in sepsis prophylaxis." (PMID 39544938, 2024). "Thus, moderate inhibition of immune cell migration by AQP5 inhibitors could be beneficial in sepsis." (PMID 38203778, 2024). "The inhibition of AQP5 expression could, thus, become a new therapeutic approach in sepsis therapy." (PMID 38203778, 2024). "We recently described a functionally important AQP5 promoter methylation site (nt-937) linked to the binding of the inflammatorily acting nuclear transcription factor NF-κB, accompanied by increased methylation in sepsis non-survivors." (PMID 36233114, 2022). "Consequently, the AQP5 promoter methylation might be influenced by the AQP5 (-1364A/C) genotype and could be a mechanism influencing AQP5 expression in sepsis." (PMID 36233114, 2022). "Thus, the AQP5 -1364A/C promoter SNP may also impact on the development of AKI related outcomes in sepsis that can compositely be assessed as major adverse kidney events within 30 days (MAKE30)." (PMID 32272738, 2020). "Thus, the association of the AQP5 SNP with altered survival and AKI incidence in sepsis could be the result of a different RAAS suppression among the AQP5 genotypes." (PMID 32272738, 2020). "In the context of sepsis, there is growing evidence that epigenetic modifications can affect protein expression; hence, AQP5 promoter methylation might be a mechanism influencing AQP5 expression." (PMID 31811204, 2019). "Therefore we concluded that the AQP5 genotype and AQP5 protein expression seem to alter neutrophil cell migration and may influence survival in sepsis by altering neutrophil cell migration." (PMID 29449936, 2018).
Sepsis (continued). "Hence AQP5 might be a key protein in inflammation and depict a novel target for developing sepsis therapeutics." (PMID 29449936, 2018). "This study suggests that AQP5 might be an important protein in LPS induced systemic inflammation and identifies the influence of AQP5 expression on immune cell migration as a potential mechanism by which the AQP5 expression affects survival in sepsis." (PMID 27871297, 2016). "Therefore AQP5 might be a key protein in inflammation and depict a novel target for developing sepsis therapeutics." (PMID 27871297, 2016). "In sepsis, AQP1, AQP4, AQP5, and AQP9 have been shown to significantly affect organs like the brain, heart, lungs, kidneys, and liver." (PMID 39544938, 2024). "The methylation status of the Aqp5 promoter cytosine site (nt-937) was linked to both NFkB binding and Aqp5 expression and may be prognostically relevant in sepsis as higher methylation is associated with sepsis non-survivors." (PMID 36768212, 2023). "Several studies showed that AQP3 is essential for T cell function and macrophage migration and that AQP5 and AQP9 regulate neutrophil cell migration and impact sepsis survival." (PMID 29449936, 2018). "However, as AQP5 also forms a pore permeable to H2O2, its potential role in sepsis must be discussed." (PMID 38203778, 2024). "AQP5 inhibition with methazolamide and furosemide has demonstrated efficacy in reducing immune cell migration and lung injury, suggesting its potential in treating acute lung injury (ALI) in sepsis." (PMID 39544938, 2024). "The sulfonamides methazolamide and furosemide reduced AQP5 expression in REH cells, while methazolamide could also reduce cell migration, suggesting that methazolamide has the potential to be used in sepsis prophylaxis." (PMID 39768394, 2024). "Although the exact mechanisms linking the AQP5 -1364A/C SNP to AKI and outcome in sepsis cannot be pinpointed by this observational study, a few speculations can be made." (PMID 32272738, 2020). "AQP5 mRNA expression in the whole blood of sepsis non-survivors was significantly greater compared to non-survivors (p = 0.037)." (PMID 31811204, 2019). "Aquaporin 5 (AQP5) expression impacts on cellular water transport, renal function but also on key mechanisms of inflammation and immune cell migration that prevail in sepsis and ARDS." (PMID 30517197, 2018). "Interestingly, AQP3, AQP5, and AQP9 are critical in the immune system due to their role in immune cell migration, where AQP5 and AQP9 regulate neutrophil cell migration and impact sepsis survival." (PMID 36212456, 2022). "By contrast, the other six positions and overall methylation analysis across the complete AQP5 nt-547 to nt-1081 promoter region revealed no statistical differences between sepsis survivors (17.2%, IQR: 14.7–18.8) and non-survivors (17.9%, IQR: 15.5–20.2, p = 0.158)." (PMID 31811204, 2019).
pulmonary edema (18 papers, 2013 to 2025). Accumulation of fluid in the lung tissues causing disturbance of the gas exchange that may lead to respiratory failure. "According to studies, AQP1 and AQP5 are involved in the development of pulmonary edema caused by ALI." (PMID 36820212, 2023). "A change in either AQP1 or AQP5 expression may represent a response to inflammation-associated pulmonary edema, and it may be causal in the formation of pulmonary edema." (PMID 27455237, 2016). "Decreased lung AQP1 and AQP5 expression may be associated with pulmonary edema development and increased severity of lung injury and pulmonary edema, which may provide an additional mechanism for pancreatitis-associated lung injury." (PMID 25009607, 2014). "This study demonstrated that in the modeling group, AQP5 fluorescence was decreased, expression was downregulated, AQP5 channels were closed, and pulmonary edema was developed in contrast with the control group." (PMID 37165489, 2024). "After lipopolysaccharide (LPS)-induced diffuse vascularization, AQP5 expression was reduced in pulmonary edema." (PMID 36820212, 2023). "Another study using an ALI mouse model focusing on the expression of AQP1, AQP3, AQP4 and AQP5 suggested AQP1 and AQP5 to play important roles in the abnormal fluid transport in ALI and their association with the development of pulmonary edema." (PMID 33673336, 2021). "In the current study, different doses of TFENF were found to promote alveolar fluid transport by regulating AQP-1, AQP-5, αENaC, βENaC, and Na+-K+-ATPase to reduce pulmonary edema." (PMID 34887746, 2021). "Although there is a paucity of information to date regarding the relationship between ROCK and AQP5, our results indicate that fasudil ameliorates LPS-induced pulmonary edema through upregulating the expression of AQP5." (PMID 28963443, 2019). "Towne JE demonstrated that the expression levels of AQP-1 and AQP-5 decreased in lungs with pulmonary edema (PE) following viral infection." (PMID 28577538, 2017). "Previous studies have confirmed that aquaporin 1 (AQP1) and AQP5 expressions were positively related to the severity of pulmonary oedema and inflammation, while antiasthmatic treatment could reduce asthma by increasing the levels of AQP1 and AQP5." (PMID 41280738, 2025). "Thus, it is suggested that fasudil ameliorates LPS-evoked pulmonary edema by increasing the expression of AQP5 and occludin." (PMID 28963443, 2019). "In this study, we hypothesized that aquaporin 5 (AQP5) which is one kind of water channels may play a role in preservation of alveolar epithelial barrier integrity in high altitude pulmonary edema (HAPE)." (PMID 24274330, 2013). "In addition, recent studies demonstrated that the expression levels of AQP1 and AQP5 in the lung decreased in viral infection model of pulmonary edema." (PMID 23741323, 2013). "Another study shows that AQP5 is strongly expressed in alveolar epithelial cells and is notably impaired after 3–14 days of hyperoxia treatment, suggesting that AQP5 is important for water movement in alveolar epithelial cells and its abnormal expression may lead to pulmonary edema." (PMID 33673336, 2021). "Correspondingly, following the administration of the three anti-asthmatic drugs, despite a reduction in pulmonary edema, there was an increase in the mRNA and protein expression of AQP1 and AQP5." (PMID 39440058, 2024). "It plays an important role in maintaining respiratory water permeability in physiological condition, and in lung diseases, such as acute lung injury, pulmonary edema, COPD, asthma, and the expression of AQP5 decreases." (PMID 39687635, 2024). "The severity of pulmonary edema formation is judged by the D/W ratio and the protein expressions of AQP-1 and AQP-5." (PMID 35123524, 2022). "The N. fordii water decoction promotes the expression of AQP-1 and AQP-5 in ALI and increases the clearance and transfer of lung water, improves water metabolism, and reduces pulmonary edema." (PMID 34887746, 2021).
pulmonary edema (continued). "In this study, the low expression of AQP1 and AQP5 don’t successfully eliminate alveoli and interstitial water after SAP, therefore, which leads to the pulmonary edema and injury." (PMID 28577538, 2017).